QKI (QKI, KH domain containing RNA binding)
Diseases named in the same sentence as QKI in open-access papers (continued):
Sharing a sentence is not in itself a finding about the gene and the disease.
tumor (continued). "miR-200 blocks the expression of QKI in tumor endothelial cells, leading to increased production of QKI, thereby promoting angiogenesis and nutrient supply." (PMID 39479357, 2024). "QKI also regulates the alternative splicing of macroH2A1 pre-mRNA, thereby inhibiting tumor cell proliferation." (PMID 38782769, 2024). "In all cases examined (n = 9), QKI was more expressed in the metastatic lesion with respect to the primary tumor." (PMID 38325381, 2024). "Compared to matched normal tissues, these patients had significantly reduced QKI mRNA expression in their tumor tissues, with a notable correlation between low QKI expression and postoperative recurrence." (PMID 39479357, 2024). "Numerous studies have indicated that QKI can modulate tumor growth by enhancing the stability of non-coding RNAs, selective splicing, and cellular cycle regulation, and it influences epithelial-mesenchymal transition (EMT) to promote tumor metastasis." (PMID 39479357, 2024). "For example, a study showed that QKI can promote the biogenesis of circSLC7A6, which is a type of circRNA with tumour inhibitory activity." (PMID 37428781, 2023). "Histologic analysis indicated that tumor samples derived from Ago-miR-497 treatment had a significantly decreased QKI expression than Ago-miR-NC tumors, similarly the proliferation marker PCNA was also inhibited." (PMID 37171386, 2023). "The QKI protein, which plays a dual functional role as a tumor promoter and tumor suppressor, has been reported in some studies." (PMID 37524698, 2023). "After data correction, an analysis of differential expression showed that the expression of QKI in tumour tissue samples of oesophageal carcinoma patients was significantly upregulated compared with those in normal control samples." (PMID 37428781, 2023). "For instance, QKI served as a tumor suppressor and inhibited gastric carcinogenesis via alternative splicing of the histone macroH2A1." (PMID 35614517, 2022). "Quaking RNA-binding protein (QKI) regulates angiogenesis, embryogenesis, glial cell differentiation, apoptosis, and transcription, and it also regulates tumor cell metabolism, differentiation, proliferation, and immunity." (PMID 36483738, 2022). "QKI is a tumor suppressor in various human cancers, including oral, colon, gastrointestinal, and prostate cancers." (PMID 35600368, 2022). "In summary, QKI promoter methylation is a tissue-specific marker of CRC that can distinguish CRC tissues from the tumor or normal tissues of other cancer types." (PMID 36017498, 2022). "We first studied the putative functions of QKI-6 in NSCLC by comparing QKI mRNA expression in tumor and normal tissues." (PMID 35600368, 2022). "When analyzing QKI expression with clinicopathological variables, we found that QKI level was significantly associated with NSCLC tumor invasion and clinical stage." (PMID 35600368, 2022). "QKI protein levels were significantly lower in tumor tissues than in normal tissues in four matched pairs of NSCLC and normal tissues." (PMID 35600368, 2022). "YAP is negatively regulated by QKI, which regulates cell contact inhibition and inhibits proliferation and invasion of tumor cells via Wnt and GPCR signaling pathways." (PMID 36483738, 2022). "Palbociclib inhibits angiogenesis and tumor progression by disrupting the miR-200b/QKI/CCND1 axis, leading to CDK 4/6-cyclin D1 complex disruption." (PMID 36498861, 2022). "Overexpression of miR-200b inhibited tumor angiogenesis through downregulation of QKI in tumor endothelium." (PMID 34439268, 2021). "Many studies have revealed that QKI is a crucial tumor suppressor that prevents the initiation and progression of various malignancies." (PMID 32931453, 2020). "In ectopic-implantation nude mice model, QKI depletion significantly increased tumor sizes and initiation rates." (PMID 32047543, 2020). "After studying the role of QKI in vitro, we wanted to confirm the inhibitory role of QKI in tumor initiation in vivo." (PMID 32047543, 2020).
tumor (continued). "QKI, which is recognized as a tumor suppressor in a wide range of cancers, is highly connected in the network, which can play a significant part in the prognosis induced by splicing events." (PMID 32831016, 2020). "Tissue microarrays showed that the expression of QKI genes, and especially QKI-6, was significantly decreased in tumor tissues compared with these in normal kidney tissues." (PMID 32047543, 2020). "The RNA-binding protein QKI is an important factor that attracts researchers' attention for its key role in tumor cell initiation and differentiation in various studies." (PMID 32047543, 2020). "We conducted HE-staining and immunofluorescence staining for CD31 in the tumor mass, which showed a significant increase of vascularization in the QKI knockdown group." (PMID 32047543, 2020). "The second mechanism is through loss of the N-terminal of QKI, resulting in downregulation of the tumor-suppressor activity of QKI." (PMID 31007851, 2019). "Previous studies showed that QKI possesses the tumour suppressor activity in human cancers by interacting with the 3'‐untraslated region (3'‐UTR) of various gene transcripts via the STAR domain." (PMID 31449345, 2019). "In the next step, we detected higher QKI expression levels in GC tumour tissues relative to adjacent normal stomach tissues among 40 patients by immunohistochemistry." (PMID 30717751, 2019). "QKI was a general tumor suppressor in a variety of human cancers by controlling gene expression post-transcriptionally, including regulating RNA alternative splicing, RNA stability, RNA processing etc23,32–37." (PMID 31562301, 2019). "By comparing exon usage and QKI expression in tumours, we found that the QKI alternative splicing signature is conserved across a range of epithelial‐derived tumours, indicative of their direct contributions to cancer progression." (PMID 29871889, 2018). "ADAMTS1 and QKI were identified as possible PCa tumor suppressors, as their expression was down-regulated, respectively, in metastatic CRPC and in poorly differentiated PCa." (PMID 29216878, 2017). "Our findings suggest that when QKI-miR-155 reciprocal regulation becomes dysfunctional, enhanced miR-155 activity drives tumor development and evasion of the immune response." (PMID 26337206, 2015). "The expression of QKI is also related to tumor angiogenesis." (PMID 39479357, 2024). "Furthermore, QKI is subject to methylation of its promoter region and the impact of the tumor microenvironment." (PMID 39479357, 2024). "The QKI protein can exert anti-tumor effects through immune regulation." (PMID 39479357, 2024). "Whether these effects are features shared by QKI in all tumor cells or are influenced by tumor heterogeneity and whether they have different effects on various tumor cells remain unknown." (PMID 36831493, 2023). "Together, these results suggest that miR-497 inhibits EC tumor growth via targeting QKI in vivo." (PMID 37171386, 2023). "Moreover, Western blot analysis showed that the CDK4 and CDK6 expressions were downregulated, whereas p21 expression was upregulated in tumor tissues from mice bearing QKI‐5 overexpressing cells compared with mice bearing control cells." (PMID 36172919, 2023). "The function of QKI was first glimpsed in brain tumors, suggesting that it may have a role in tumor suppression." (PMID 36017498, 2022). "Furthermore, QKI protein expression was higher in normal tissue than in NSCLC CPTAC (Clinical Proteomic Tumor Analysis Consortium) samples (n = 222)." (PMID 35600368, 2022). "Additionally, pharmacologic inhibition of type II PAKs by PF-3758309 blocked LNCaP QKI-OE tumor growth in vivo." (PMID 36672609, 2022). "Moreover, decreased QKI expression was closely correlated with high tumor grade, poor differentiation, and poor survival." (PMID 32047543, 2020). "The positive correlation between Loc490 and QKI levels in tumor tissues further suggested that there could be a relationship between Loc490 and QKI." (PMID 32931453, 2020).
tumor (continued). "In vivo, the knockdown of QKI promoted tumor growth and upregulated the expression of HIF-1α." (PMID 32047543, 2020). "Moreover, less differentiated and more aggressive PCa cases display lower QKI and MacroH2A1.1 transcripts levels, as expected for putative tumor suppressors." (PMID 31164793, 2019). "Similarly, ARGLU1 and CIRBP were lower expressed in tumor compared to metastatic tissue, while QKI was higher expressed." (PMID 30940821, 2019). "Here, we found that QKI promoted tumor formation in human mammary epithelial cells." (PMID 30059005, 2018). "Several studies have indicated QKI plays tumour suppressive roles in cancer, but its ability to regulate EMT remains unclear." (PMID 29871889, 2018). "Up to now, studies of QKI in tumor metastasis have been rare." (PMID 29861871, 2018). "Quaking(QKI) is an RNA binding protein, and it has been shown to serve as a tumor suppressor." (PMID 29861871, 2018). "Therefore, in addition to enhancing cell migration and invasion, QKI appears to concurrently reduce tumour formation capacity in mesHMLE cells." (PMID 29871889, 2018). "This study and those of others strongly suggest that QKI functions as a tumor suppressor." (PMID 24722255, 2014). "The RBM proteins and QKI could thus be considered tumor suppressors." (PMID 34065983, 2021). "Thus, QKI may play a dual role in cancer progression, limiting the initial formation of tumours but increasing their subsequent invasiveness through regulating the splicing of different target genes, such as through promotion of mesenchymal ENAH splicing." (PMID 29871889, 2018). "To assess whether the miR‐200c–QKI inverse relationship is observed more broadly across other cancers, we examined the pan TCGA panel, which demonstrated QKI displays a strong negative recurrence score with miR‐200c across the 10 represented tumour types." (PMID 29871889, 2018). "Silencing of CAHM, in addition to QKI, may therefore be important for tumor development." (PMID 24799664, 2014). "Because QKI acts as a negative regulator of TGF-β, the reduced QKI resulted in enhanced TGF-β/Smad signaling and tumor angiogenesis." (PMID 41222726, 2025). "Besides, QKI could also regulate mRNA stability of target genes to repress tumor progression." (PMID 38485986, 2024). "QKI is a classical RBP that belongs to the STAR family and is accepted as a tumour suppressor in CRC as well as many other human cancers." (PMID 38041531, 2024). "Conversely, certain SFs, including QKI, RBM5, RBM6, and RBM10, act as tumor suppressors and exhibit anti-cancer characteristics." (PMID 39004679, 2024). "We now show that the splicing signature of tumor cells can also be employed to accurately distinguish the PDAC molecular subtypes and that QKI is a key determinant of the basal-like splicing pattern." (PMID 38325381, 2024). "Previously, we revealed that QKI promotes AGO2/let-7b-mediated gene silencing and functions as a tumor suppressor in HeLa cells." (PMID 39308343, 2024). "We also found that mechanistically, NONHSAT136151 exerted a pro‐oncogenic function by directly interacting with QKI (Quaking), a crucial RBP that is considered a tumour suppressor." (PMID 38041531, 2024). "Therefore, QKI may influence tumor immune modulation by participating in inflammation." (PMID 39479357, 2024). "Three neighboring genes residing this locus are PRKN (PARKIN), PACRG (Parkin Coregulated Gene), and QKI (QUAKING), and both PRKN and QKI have been shown to be tumor suppressors in GBM." (PMID 36051438, 2022). "The mechanism behind the MYB–QKI fusion has been well studied and is proposed to be a tripartite mechanism: MYB is overexpressed, the regulatory domain of MYB is truncated and the tumor repressor function of QKI is lost." (PMID 35169893, 2022). "Previous TCGA analyses have appointed QKI as the common gene shared among the 6q26 chromosome alterations in GBM, alluding to its dominance as the tumor suppressor effector housed in this region." (PMID 36051438, 2022).
tumor (continued). "Most RBPs (11 out of 16) act as oncogenes and only 5 (TIA1, TTP, QKI, ESRP1, CELF2, and QKI) present tumor suppressive abilities." (PMID 31440515, 2019). "Accordingly, xenograft assay showed that GAS5 overexpression attenuated tumor growth, while GAS5 silencing promoted tumor growth in vivo, which could be reversed by knockdown or overexpression of IGF2BP2 or QKI." (PMID 38782769, 2024). "The YY1 binds to the super-enhancer and promoter of QKI, leading to its abnormal activation, subsequently inducing the formation of circRNAs in HCC and triggering epithelial-mesenchymal transition (EMT) and tumor metastasis." (PMID 39479357, 2024). "Finally, we constructed a model using four genes, RBMS1, ZC3HAV1, QKI, and RBM38, to calculate the Tumor Immune Dysfunction and Exclusion (TIDE) score." (PMID 37628671, 2023). "Two neighboring genes in this region, QKI and PRKN have been appointed as tumor suppressors in GBM." (PMID 36051438, 2022). "Moreover, we observed that 21 splicing factor genes showed significantly differential AS between SS and tumor-adjacent tissues, such as HNRNPA1, PTBP2, QKI, RBFOX2, and TRA2A." (PMID 36118864, 2022). "QKI plays a role in tumor angiogenesis via CCND1-mediated endothelial cell cycle progression by binding and stabilizing cyclin D1 mRNA; in turn, miR-200b influences cell cycle progression, angiogenesis, and metastasis by negatively regulating QKI expression." (PMID 36498861, 2022). "We found that 10 CpG sites in the QKI promoter were specifically hypermethylated in CRC tissues but not in tumor tissues from 30 other cancer types or normal tissues." (PMID 36017498, 2022). "Moreover, downregulation of miR-362-5p promoted the protein levels of QKI, MacroH2A1.1, PARP-1, p27 in tumor tissues, while reduced the protein levels of Cyclin D, MacroH2A1.2, c-Fos, and E2F1." (PMID 32194406, 2020). "We next examined whether the expression of QKI and RBFOX1 also correlated with mesenchymal features in murine or human tumor samples." (PMID 30059005, 2018). "The mammalian GLD-1 homologue QKI has been reported to co-localize and interact with ALG2, and recently QKI was shown to directly interact with and stabilize miR-20a, revealing a role for QKI in tumour suppression." (PMID 24258276, 2013). "The role of QKI in the tumor microenvironment should not be overlooked." (PMID 39479357, 2024).
cancer (67 papers, 2014 to 2025). A tumor composed of atypical neoplastic, often pleomorphic cells that invade other tissues. "Hypoxia, a hallmark of cancer, inhibited QKI expression which controlled the biogenesis of circ_0001766 via back-splicing of PDIA4 exons 2 and 3 in CRC." (PMID 40263288, 2025). "The QKI locus is a common fragile site, characterized by significant genomic instability and resulting frequently mutations of various cancers." (PMID 39479357, 2024). "Recent studies suggested that the loss or overexpression of QKI was related to the process of various human disorders or/and diseases including muscle-differentiation, diabetic heart disease, and cancers." (PMID 37171386, 2023). "MiR-200c and miR-375 exhibit the translational repression of Quaking (QKI), a well-characterized RBP, to affect QKI-mediated AS, thereby influencing cancer-associated epithelial cell plasticity." (PMID 35427215, 2022). "QKI has long been associated with neurological diseases and cancers, modulating various pathways through both transcriptional and post-transcriptional regulation." (PMID 36051438, 2022). "Functional enrichment analysis showed that the inferred QKI modulators were highly associated with regulation progress of some hallmark cancer genes, including ARMH4, LINC01268, PDP2, LAPTM4B, and CD7." (PMID 32273884, 2020). "Low levels of QKI expression in multiple cancer types—including CRC—were associated with an increase in macroH2A1.2 levels and a concomitant increase in macroH2A1.1 levels." (PMID 31096699, 2019). "Genome-wide analysis of QKI-dependent splicing by RNA-Seq identified some cancer-associated splicing changes as its targets." (PMID 24722255, 2014). "Similarly, miR-200c and miR-375 exert translational repression on Quaking (QKI), an RBP, which affects QKI-mediated AS and consequently influences the plasticity of cancer-associated epithelial cells." (PMID 40129920, 2025). "The activity of QKI is associated with cancer progression and therapeutic resistance." (PMID 39550559, 2024). "Down-regulation of QKI in NSCLC causes a number of cancer-associated splicing events." (PMID 24722255, 2014). "Moreover, the critical gatekeeper of the epithelial state, miR‐200c, could induce mRNA alternative splicing through suppressing QKI expression and impact cancer‐associated epithelial cell plasticity." (PMID 36172919, 2023). "Overall, these findings suggest that lower QKI and MacroH2A1.1 expression levels might be associated with worse PCa-related survival, a hypothesis that follows the same reported for other cancer models, but which requires further investigation in a larger cohort of PCa patients." (PMID 31164793, 2019). "The reduced nuclear localization of QKI likely diminishes its ability to promote PABPN1 LLPS in cancer cells, as validated by overexpression of QKI and QKI-NLS, and further supported by the effect of arsenite treatment." (PMID 40052530, 2025). "A series of studies have further elucidated that QKI has key roles in cardiovascular development, cell differentiation, metabolism, and cancer progression." (PMID 38485986, 2024). "QKI regulates splicing of many mRNAs during EMT, which contributes to morphological and phenotypic changes associated with increased cancer invasiveness." (PMID 38019605, 2024). "miR‐155 directly targets QKI that results in the acquisition of cancer stem cell‐like (CSC‐like) properties in liver cancer." (PMID 36172919, 2023). "Instead, we utilized existing cancer cell line data on their drug sensitivity to identify drug-gable signaling pathways active in QKI-overexpressing tumors." (PMID 36672609, 2022). "By integrating genome-wide methylation data from tissues and cell lines of multiple cancer types, this study revealed that methylation of the QKI promoter was a CRC-specific marker." (PMID 36017498, 2022). "Here, we evaluated the methylation status of QKI by integrating the methylation data of tissues and cell lines of multiple cancer types." (PMID 36017498, 2022).